TRPM8 (transient receptor potential cation channel subfamily M member 8)
Diseases named in the same sentence as TRPM8 in open-access papers (continued):
Sharing a sentence is not in itself a finding about the gene and the disease.
dry eye (18 papers, 2015 to 2025). "Blockade of TRPM8 alleviates mechanical corneal hyperalgesia and spontaneous ophthalmalgia associated with dry eye." (PMID 39500360, 2024). "Antagonizing TRPM8 for alleviating dry eye-associated cold allodynia can reduce basal tearing and aggravate dry eye symptoms." (PMID 31831729, 2019). "Aging, a risk factor for dry eye symptoms, may be associated with a change in the morphology and firing patterns of the corneal cold-sensitive nerves with TRPM8." (PMID 33424555, 2020). "TRPM8 channels are widely recognized to be overactivated in dry eye-related conditions, leading to ocular pain and cold allodynia." (PMID 40429806, 2025). "In an in vitro model of dry eye, 3-iodothyronamine (3T1AM), an endogenous thyroid hormone metabolite, activates TRPM8 at a constant temperature in the human conjunctival epithelial cells (HCE)." (PMID 36145607, 2022). "In this work, two stereoisomers of AR-15512, a TRPM8 agonist currently in clinical trials for the treatment of the very common ophthalmological disorder dry eye, were synthesized and fully characterized." (PMID 33572112, 2021). "Correlating well with this observation, more cold-sensitive neurons responded to capsaicin in the cornea-projection area of TG from dry eye mice, suggesting an enhanced nociceptive function of corneal TRPM8+ sensory fibers under dry eye conditions." (PMID 31831729, 2019). "C3 is a promising candidate for study of TRPM8 function on the eye surface and for relief of dry eye discomfort." (PMID 28651550, 2017). "Taken together, TRPM8 agonists should be evaluated in various dry eye animal models to determine if they reduce dry eye symptomology and dampen TRPV1-induced inflammation and corneal opacification." (PMID 26605361, 2015). "Research shows increased TRPM8 expression and function in injured trigeminal ganglion cold-sensitive neurons, leading to abnormal cold sensation, ongoing firing, and increased tear production, which are all core features of post-injury dry eye discomfort." (PMID 40940733, 2025). "However, topical formulations of TRPM8 modulators directed to attenuate receptor pathological overactivity in conditions such as dry eye syndrome or pruritus have reported promising results." (PMID 40123199, 2025). "Notably, positive results of the phase 3 COMET trial of AR‐15512, a novel formulation of a TRPM8 drug candidate for dry eye syndrome, were announced." (PMID 40123199, 2025). "However, TRPV1 is significantly upregulated in TRPM8+ cold-sensing neurons in dry eye mice, compared with sham-operated mice." (PMID 31831729, 2019). "In a clinical context, thermosensitive TRPM8 function in nerve fibres may be relevant for dry eye syndrome treatment since corneal cooling below 23°C increased lacrimation through TRPM8 activation whereas warming had an opposite effect." (PMID 26605361, 2015). "Additionally, some patents reported the use of TRPM8 agonists to relieve ocular pain and dry eye." (PMID 36145607, 2022). "There are reports of overexpression of TRPM8 in DED, which has been the principal theory for explaining the cold allodynia of patients with dry eye." (PMID 39839966, 2025). "Under pathological dry eye conditions, the expression of TRPV1 is further upregulated in TRPM8+ neurons." (PMID 31831729, 2019). "In a murine dry eye model, the TRPV1 channel plays a major role in hypertonic saline-induced nocifensive behavior, while the TRPM8 channel is less important." (PMID 30445735, 2018). "While thyronamine activates TRPM8, TRPV1 stimulation by CAP is blocked, thereby protecting the dry eye." (PMID 29238714, 2017). "After establishment of chronic dry eye (4 weeks after surgery), we found that the percentage of TRPM8+ neurons is not altered." (PMID 31831729, 2019).
dry eye (continued). "The antagonism of TRPM8 by N-(3-aminopropyl)-2-{[(3-methylphenyl)methyl]oxy}-N-(2-thienylmethyl) benzamide (AMTB) has also been considered for DED treatment, since evaporative cooling and hyperosmotic stimuli trigger dry eye pain as well as blinking." (PMID 30445735, 2018). "Antagonism of TRPM8 has also been considered for DED because evaporative cooling and hyperosmotic stimuli may trigger dry eye pain." (PMID 28651550, 2017). "Indeed, using normally innocuous doses of cryosim-3, activation of corneal TRPM8+ sensory fibers evoked nocifensive behavior in dry eye mice but not in sham-operated mice." (PMID 31831729, 2019). "Thus, TRPM8 agonists may indirectly reduce dry eye pain by maintaining the tear film rather than directly disrupting corneal nociception." (PMID 40429806, 2025). "Although our gene deletion and pharmacological blockade assays have shown that TRPV1 is necessary for dry eye-associated cold allodynia, it is unclear whether the upregulation of TRPV1 in TRPM8+ neurons alone (without dry eye) is sufficient for generating cold allodynia." (PMID 31831729, 2019).
glioblastoma (17 papers, 2009 to 2025). The most malignant astrocytic tumor (WHO grade IV). "This assumption is in contradiction to a retrospective clinical study which concluded that higher TRPM8 mRNA abundance in the tumor associates with better overall survival of glioblastoma patients." (PMID 29221175, 2017). "Notably, this increase was higher in U251 than in T98G cells consistent with the degree of TRPM8 knockdown-associated radiosensitization in both glioblastoma lines." (PMID 29221175, 2017). "Menthol, a drug that specifically targets TRPM8, enhances Ca2+ influx by upregulating TRPM8 expression in glioblastoma, thus augmenting tumor cell migration." (PMID 40535121, 2025). "In bone cancer, pancreatic adenocarcinoma, glioblastoma, and bladder cancer, it was also demonstrated that TRPM8 promotes cell proliferation and migration." (PMID 37033630, 2023). "For example, in gastric, pancreatic, and bone cancers, adenocarcinoma, and glioblastoma, TRPM8 promotes invasion and metastasis." (PMID 37033630, 2023). "In osteosarcoma and glioblastoma, TRPM8 promotes cell proliferation through the modulation of cyclin D1 and cyclin-dependent kinase 4 (Cdk4) expression." (PMID 37033630, 2023). "It has been described that in glioblastoma, TRPM8 channels modulate the expression of apoptosis-related factors through regulation of the p38/MAPK (mitogen-activated protein kinases) pathway." (PMID 37033630, 2023). "In human glioblastoma cells, the TRPM8 channel stimulated cell progression to the S phase, and mitosis, inducting cyclin-dependent kinase CDC2, Ca2+/calmodulin-dependent protein kinase II (CaMKII) isoforms, and phosphatase CDC25C." (PMID 36844925, 2022). "As for melastatin-related subfamily member TRPM8, accumulating evidence has pointed out its crucial role in malignant cells, especially in glioblastoma." (PMID 35140788, 2022). "Activation of TRPM8 by menthol has been shown to stimulate BK K+ channel activity and migration of glioblastoma cells suggesting that TRPM8 functions as Ca2+ entry pathway in glioblastoma cells." (PMID 29221175, 2017). "TRPM8 agonists have been reported to stimulate the activity of BK Ca2+-regulated K+ channels in glioblastoma cells." (PMID 29221175, 2017). "Among 21 tested nonselective cation channels belonging to the transient receptor potential (TRP) super family, the melastatin family member 8 (referred to as TRPM8) showed highest upregulation in glioblastoma as compared to normal brain tissue." (PMID 29221175, 2017). "The exact molecular mechanisms leading to activation of TRPM8 in glioblastoma, however, are far from being understood." (PMID 29221175, 2017). "This suggests either selection of TRPM8 overexpressing and resistant glioblastoma cell clones or an adaptive response." (PMID 29221175, 2017). "ii) Ionizing radiation with doses used in the clinic for fractionated radiation therapy of glioblastoma patients induces upregulation of TRPM8 function." (PMID 29221175, 2017). "Combined, our observations suggest that TRPM8 promotes brain invasion and confers radioresistance of glioblastoma cells." (PMID 29221175, 2017). "In summary, these data indicate functional significance of TRPM8 for DNA repair and clonogenic survival of irradiated glioblastoma cells." (PMID 29221175, 2017). "Since p-(Tyr15)-cdc2 is a substrate of the phosphatase cdc25C, these data suggest a TRPM8-triggered signaling to cdc2 involving CaMKII and cdc25C in irradiated glioblastoma cells." (PMID 29221175, 2017). "In summary, the data demonstrate that glioblastoma cells express TRPM8 channels, which exert pivotal functions in cell cycle control, prevention of apoptotic cell death, migration and chemotaxis, DNA repair and radioresistance." (PMID 29221175, 2017).
glioblastoma (continued). "Combined, these data clearly indicated a cell migration and chemotaxis-stimulating role of TRPM8 channels in the human glioblastoma lines T98G and U-87MG confirming earlier reports on human DBTRG glioblastoma cells." (PMID 29221175, 2017). "The present study confirms previous data showing that TRPM8 channels constitute a Ca2+ entry pathway in glioblastoma cells and that TRPM8 channel activity stimulates glioblastoma cell migration." (PMID 29221175, 2017). "TRPM8 is aberrantly overexpressed in a variety of tumor entities including glioblastoma multiforme where it reportedly contributes to tumor invasion." (PMID 29221175, 2017). "Together, the cell cycle data suggest a functional significance of TRPM8 channels in cell cycle control of unirradiated and irradiated glioblastoma cells." (PMID 29221175, 2017). "In U251 glioblastoma cells, downregulation of Musashi-1 (MSI1) was associated with upregulation of TRPM8." (PMID 29221175, 2017). "Combined, the data suggest a highly heterogeneous TRPM8 expression in human glioblastoma specimens and established glioblastoma cell lines." (PMID 29221175, 2017). "Meanwhile, there is increasing evidence that many tumor entities highly overexpress TRPM8 channels similar to glioblastoma." (PMID 29221175, 2017). "In glioblastoma cells, addition of menthol stimulates an increase in [Ca2+]ic and their ability of migration, presumably by activating TRPM8." (PMID 26512697, 2015). "Expression of TRPM8 has also been identified in other malignancies such as lung carcinoma, colorectal melanoma, glioblastoma multiforme, neuroendocrine tumor, and oral squamous cell carcinoma." (PMID 26512697, 2015). "In addition, it has been reported that TRPM8 channels are involved in the progress of pancreatic, breast, bladder, colon, gastric, and skin cancers, glioblastoma, and neuroblastoma." (PMID 37033630, 2023). "Similar effects were observed in glioblastoma, where TRPM8 participates in cancer cell resistance." (PMID 37033630, 2023). "Similarly, in glioblastoma cell lines U-87MG and T98G were observed that the TRPM8 agonist icilin increased chemotaxis." (PMID 37033630, 2023). "TRPM8 was reported to influence the migration capacity of glioblastoma cell by bringing a significant increase in Ca2+ concentration, and consistently, TRPM8 downregulation by RNA silencing reduces tumor cell migration capacity and decreases transfilter chemotaxis." (PMID 35140788, 2022). "A combination of TRPM8 targeting and radiotherapy could be an interesting approach for future glioblastoma therapy." (PMID 34458247, 2021). "Also, TRPM8 was highly expressed in glioblastoma cell lines and its expression correlated with higher invasive and proliferative capacities." (PMID 33240883, 2020). "Likewise, in glioblastoma cells, TRPM8 channels collaborate with Ca2+-dependent IK and BK channels to generate radiogenic Ca2+ signals." (PMID 32390841, 2020). "TRPM8 upregulation and knockdown significantly increased and decreased the icilin-induced rise in intracellular free Ca2+ concentration, respectively, indicating functional expression of TRPM8 in the plasma membrane of glioblastoma cells." (PMID 29221175, 2017). "We tested in the glioblastoma cell lines U-87MG and T98G whether cell migration and chemotaxis depend on TRPM8 channel activity." (PMID 29221175, 2017). "The present study, therefore, aimed to define in vitro the functional significance of TRPM8 for the Ca2+ and biochemical signaling in glioblastoma cells, involved in cell migration and chemotaxis on the one hand and in the stress response to DNA damage by ionizing radiation on the other." (PMID 29221175, 2017). "TRPM8 inhibition or knockdown slowed down cell migration and chemotaxis, attenuated DNA repair and clonogenic survival, triggered apoptotic cell death, impaired cell cycle and radiosensitized glioblastoma cells." (PMID 29221175, 2017).
glioblastoma (continued). "Moreover, TRPM8 agonists have been reported previously to stimulate migration of glioblastoma cells." (PMID 29221175, 2017). "The documented upregulation of the androgen receptor in glioblastoma might therefore contribute to TRPM8 overexpression in the brain tumor." (PMID 29221175, 2017). "Combined, our data suggest that TRPM8 channels contribute to spreading, survival and radioresistance of human glioblastoma and, therefore, might represent a promising target in future anti-glioblastoma therapy." (PMID 29221175, 2017). "As a result, human glioblastoma upregulates TRPM8 channels to variable extent." (PMID 29221175, 2017). "Similarly, TRPM8, which is found in glioblastoma cells, plays an analogous role." (PMID 40535121, 2025). "Moreover, TRPM8 was significantly overexpressed in glioblastoma tissue samples compared to normal tissue and its expression correlated with worse prognosis and survival in glioblastoma patients." (PMID 33240883, 2020). "Although this review concentrates on the role of KCa3.1 and STIM/Orai channels in modulating Ca2+ oscillations and cell migration, it needs to be said that other channels including TRPM8 and KCa1.1, also abundantly expressed in glioblastoma cells, may also be important in these processes." (PMID 30274242, 2018). "Since TRPM8 function - as suggested by the present study - seems to be needed for both, migration and survival of irradiated cells, it is tempting to speculate that IK and BK K+ channels closely interact with TRPM8 in glioblastoma cells." (PMID 29221175, 2017). "Querying the Cancer-Genome-Atlas for MSI1 and TRPM8 mRNA abundances, however, did not confirm such an association in glioblastoma patient specimens (data not shown) suggesting that this phenomenon might be restricted to U251 cells." (PMID 29221175, 2017). "Therefore, targeting TRPM8 alone or in combination with radiotherapy, possibly might be a promising new strategy for future anti-glioblastoma therapy." (PMID 29221175, 2017). "Notably, inhibition of IK Ca2+-activated K+ channels in unirradiated and irradiated T98G cells exerted effects on cell cycle progression that differed from those observed upon TRPM8 knockdown pointing to a highly complex regulation of cell cycle by electro- and Ca2+ signaling in glioblastoma cells." (PMID 29221175, 2017). "TRPM8 affects glioblastoma (GBM) cell migration rate by stimulation with specific agonists, such as menthol and icilin, which mediated a substantial increase in [Ca2+]i, while contributes to proliferation, survival, and local tumor invasion in the case of U251 glioblastoma cells." (PMID 36844925, 2022). "Therefore, we determined the effect of the synthetic TRPM8 super-agonist icilin (3-(2-Hydroxyphenyl)-6-(3-nitrophenyl)-3,4-dihydropyrimidin-2(1H)-one) on the BK K+ channel activity in the plasma membrane of T98G glioblastoma cells by patch-clamp on-cell (cell-attached) recording." (PMID 29221175, 2017). "In this context, TRPM8-mediated regulation of RhoA/ROCK might be responsible for the pro-tumoral effect of TRPM8, as the RhoA/ROCK pathway has been involved in the proliferation and migration of glioblastoma cells." (PMID 33240883, 2020). "The present in vitro study proposes a possible functional significance of Ca2+-permeable TRPM8 nonselective cation channels for glioblastoma survival, local tumor invasion, and radioresistance." (PMID 29221175, 2017). "We have shown that menthol, a known agonist of TRPM8 ion channels found in DBTRG human glioblastoma cells, stimulates the migration of DBTRG human glioblastoma cells into scratch wounds and increases [Ca2+]i which, thereby, increases activity of BK ion channels." (PMID 19778436, 2009). "Moreover, the data strongly suggest that the observed radiosensitization by TRPM8 knockdown could not simply result from accelerated apoptotic death of the irradiated glioblastoma cells." (PMID 29221175, 2017).
glioblastoma (continued). "In addition, our experimental settings (e.g, migration, colony formation assays) did not subject the cells to any changes in osmolarity, suggesting that the documented osmosensing function of TRPM8 can also not account for the observed TRPM8 activity in glioblastoma cells." (PMID 29221175, 2017). "Whether or not TRPM8-targeting alone or in combination with radiotherapy has tolerable side effects and does effectively prolong survival has to await future preclinical studies in orthotopic glioblastoma animal models." (PMID 29221175, 2017).